LINC02636 (long independently transcribed non-coding RNA 2636)
Gene: Long non-coding RNA gene on chromosome 10 (69,994,276 to 70,054,209, reverse strand). Ensembl gene ENSG00000224222.
Diseases named in the same sentence as LINC02636 in open-access papers:
LINC02636 is named in the same sentence as 1 disease in open-access papers, as found by Europe PMC text mining. Sharing a sentence is not in itself a finding about the gene and the disease. The quoted sentences say what the papers report.
glioma (1 paper, 2024). A benign or malignant brain and spinal cord tumor that arises from glial cells (astrocytes, oligodendrocytes, ependymal cells). "We further found that the expression of SUMF1, LINC01426, AC061992.2, CARD8-AS1, AC083855.2, AC027307.2, WAKMAR2, and LINC02636, were associated with adverse progression in patients with glioma." (PMID 38460946, 2024). "The Lasso analysis revealed that the expression of LINC01426, AC061992.2, CARD8-AS1, AC083855.2, AC027307.2, AC026356.1, LYRM4-AS1, WAKMAR2, and LINC02636 were associated with adverse survival time and DSS in patients with glioma." (PMID 38460946, 2024). "Additionally, the expression of LINC01426, AC061992.2, CARD8-AS1, AC083855.2, AC027307.2, WAKMAR2, LINC02636, and SUMF1 were correlated with adverse PFI in patients with glioma." (PMID 38460946, 2024).